MYC (MYC proto-oncogene, bHLH transcription factor)
Diseases named in the same sentence as MYC in open-access papers (continued):
Sharing a sentence is not in itself a finding about the gene and the disease.
tumor (continued). "The heat map combined with GSVA score difference showed that hallmark glycolysis, tumor proliferation signature, DNA replication, G2M checkpoint and MYC targets gene signatures were more active in high glycolysis groups across 23~24 cancer types." (PMID 32635458, 2020). "The tumor cells are derived from germinal center B (GC-B) cells and usually carry the hallmark translocation involving MYC and the immunoglobulin heavy or light chain loci which results in high expression of MYC." (PMID 33261009, 2020). "As increased abundance of the MYC oncoprotein is associated with the pathogenesis of most human tumours, deciphering such novel mechanisms of MYC repression is fundamental to understanding MYC-dependent cancer initiation and progression." (PMID 32527935, 2020). "We know that MYC stimulates specific expression programs in tumor-associated macrophages, but how exactly does it help cancer to progress?" (PMID 33081056, 2020). "Our data indicate that inhibition of EIF5A hypusination reduces global levels of MYC in human and mouse cells, and causes inhibition of tumor growth." (PMID 33303756, 2020). "Here the NDRG2 gene is located, a tumor suppressor gene that has been associated with c-MYC and the TGF-β pathway in colorectal carcinogenesis, and its epigenetic silencing promotes tumor proliferation and invasiveness." (PMID 30813366, 2019). "Pyruvate kinase M2 (PKM2), a glycolysis enzyme, phosphorylates histone H3 causing dissociation of HDAC3 from CCND1 and the MYC promoter region, thereby increasing their expression, tumor cell proliferation, cell cycle progression, and brain tumor formation." (PMID 31546918, 2019). "The changes in tumor cell metabolism after EPHB4 inhibition were associated with MYC downregulation, likely mediated by the SRC/p38 MAPK/4EBP1 signaling cascade, known to impair cap-dependent translation." (PMID 31641103, 2019). "In breast cancer, stiff matrix is found to be associated with poor survival and tumor aggressiveness, probably due to the activation of MYC and the suppression of phosphatase and tensin homolog (PTEN) and homeobox A9 (HOXA9)." (PMID 30934860, 2019). "A high MYC copy number was associated with marked pigmentation (P < 0.001), high mitotic count (P = 0.021), and a large tumor basal diameter (P = 0.040)." (PMID 31848373, 2019). "We found that cellular senescence and tumor regression upon MYC inactivation in T-ALL was associated with genome-wide changes in 5mC and 5hmC patterns." (PMID 31266538, 2019). "We found that high levels of MYC mRNA are associated with high risk for tumor pathogenesis and poor prognosis in HCC." (PMID 30770740, 2019). "A senescence‐associated tumor regression following MYC inactivation has been reported in several cell contexts." (PMID 31293052, 2019). "When overexpressed, MYC is a potent oncogene, and its constitutive high-expression drives many tumor types and is often associated with cancer aggressiveness and poor prognosis." (PMID 31399583, 2019). "Recent reports have shown that FAM83H is also involved in the progression of human cancers in conjunction with tumor-associated molecules, such as MYC and β-catenin." (PMID 31215499, 2019). "Epstein Barr virus IgG in sera was determine using Enzyme-linked immunosorbant assay, IHC for EBER-1 and MYC protein in tumour sections." (PMID 32180880, 2019). "As a key element of the initiation translation complex, eIF4E participates in the translation of tumor–associated proteins, such as c‐MYC, cyclin D1, and MCL‐1 (Kosciuczuk, Saleiro, & Platanias, 2017)." (PMID 30891950, 2019). "Because BRD4 densely occupies super enhancers, its inhibition reduces MYC transcription causing an anti-tumor effect." (PMID 31226848, 2019). "Tumours with high MYC and high ATR expressions were significantly associated with vascular invasion, higher tumour grade, pleomorphism, high mitotic index and high-risk Nottingham Prognostic Index (NPI) (all adjusted p values ≤ 0.01)." (PMID 30746633, 2019).
tumor (continued). "MYC is one of the most studied oncogenes, and its misexpression is associated with various tumor types including meningioma, Burkitt's lymphoma, medulloblastoma and hepatocellular carcinoma." (PMID 30881374, 2019). "A subclonal NRAS G13A mutation (VAF 0.03) was detected in the oligoclonal tumor arising from MYC, BCL2, P53dd transduced cells." (PMID 31586074, 2019). "In the current study, we provide the first clinical evidence that high ATR in MYC overexpressed tumours is associated with aggressive cancer and poor survival." (PMID 30746633, 2019). "The concept that SNF5 is a coactivator for MYC, however, is at odds with its role as a tumor-suppressor, and with observations that loss of SNF5 leads to activation of MYC target genes." (PMID 31043611, 2019). "By combining the Rosa26-DM.lsl-MYC allele with lsl-KRasG12D, we aimed to model tumour evolution in an important subset of human non-small cell lung cancers." (PMID 31032816, 2019). "Dysregulation of MYC is often caused by tumor-specific super-enhancers in the region surrounding the MYC gene." (PMID 30247654, 2019). "T‐025 caused synergistic cell death with MYC activation and showed a promising anti‐tumor efficacy in a MYC‐driven mouse spontaneous tumor allograft model." (PMID 29769258, 2018). "SLC7A5 mRNA and protein expression was significantly associated with the expression of the key regulator of tumour cell metabolism, c-MYC, specifically in luminal B tumours only (p = 0.001)." (PMID 29566741, 2018). "Proteins associated with tumor development and suppression like MYC and PTEN play a major role in the turnover of ribosomes by regulating the expression of RPs and S6K activity, respectively." (PMID 29568375, 2018). "Because MYC has proven notoriously ‘undruggable’ and high tumor ODC activity has been linked to lower survival in cancer patients, inhibition of ODC by DFMO is a promising therapeutic strategy." (PMID 29419804, 2018). "Our IHC experiment reveals substantial accumulation of β-catenin and MYC in tumor cells with D32Y and G34E mutations." (PMID 30223484, 2018). "We observed that both SOX2 and MYC expression were associated with high grade tumor histology, while OCT4 expression correlated with low grade histology." (PMID 30510261, 2018). "Together, these data indicate that GATAD2B physically associates with MYC and that MYC is required for GATAD2B-dependent tumor growth in KRASG12D-expressing cells." (PMID 30013058, 2018). "In many cancer types, MYC overexpression is associated with aggressive disease and alterations in MYC expression levels play an essential role in tumor development and progression." (PMID 29741575, 2018). "The tumor suppressor FBW7 targets oncoproteins such as c-MYC for ubiquitylation and is mutated in several human cancers." (PMID 29346117, 2018). "Aberrant transcriptional activation of the MYC oncogene occurs frequently in tumor cells and is associated with tumor aggression." (PMID 29641996, 2018). "MYC inactivation can cause sustained tumor regression in a variety of cancer types, eliciting oncogene addiction by triggering cellular senescence and apoptosis." (PMID 30453475, 2018). "By a genome-wide search for amplified loci significantly associated with complex genome rearrangements across eight tumor entities, we identified the MYC locus as strongly associated with catastrophic events." (PMID 30420702, 2018). "Literature shown that CIP2A inhibited the tumor suppressor protein PP2A which downregulated phophorylation of AKT, a hallmark of cancers and stabilized the proto-oncogene, MYC in tumor cells." (PMID 30044786, 2018). "Collectively, these results suggest that MYC expression is closely associated with tumor cell growth in AMU‐ML2 cells." (PMID 30524948, 2018).
tumor (continued). "Elevated expression of the c-MYC transcription factor occurs in a broad spectrum of human cancers and is associated with tumor aggression and poor clinical outcome." (PMID 29641996, 2018). "Expression of the stem cell factors SOX2, OCT4, NANOG, and MYC has been linked to tumor malignancy in several cancers." (PMID 30510261, 2018). "Experimentally, inactivation of MYC oncogene in HCC is sufficient to lead to tumor regression associated with proliferative arrest, differentiation, and apoptosis." (PMID 29464015, 2018). "Overexpression of MYC and cyclin D1 can cause bypass of cell cycle checkpoints and promote tumor cell proliferation." (PMID 29423038, 2018). "FBXW7 encodes for a tumour suppressive protein, which regulates ubiquitin-mediated degradation of various oncoproteins (cyclin E, c-MYC, NOTCH)." (PMID 30344950, 2018). "MYC overexpression which often leads to MYC oncogene addiction has been associated with aggressive phenotype in many tumor types." (PMID 29463565, 2018). "Copy number variant analysis of genome-wide methylation data showed MYC amplification in the primary tumor that was conserved in neurospheres cultures and xenograft transplantations." (PMID 28417956, 2017). "Tumor regression was associated with global epigenetic changes, highlighting the notion that MYC controls chromatin organization in a genome-wide fashion." (PMID 29100357, 2017). "MYC is an estrogen responsive gene and its overexpression is implicated in hormone-independence in ER+ breast cancer cell and tumor models." (PMID 28696357, 2017). "MYC over-expression promotes tumorigenesis, and transient down-regulation of MYC below a certain level causes tumor regression in animal models." (PMID 29321817, 2017). "ERK and PI3K pathways cooperate with MYC expression in tumor cells and increase its stability, as well as mutations in certain domains of MYC." (PMID 28375188, 2017). "We also assessed which of the known cancer drivers, KIT, EGFR or MYC, had the closest association with tumor progression." (PMID 29088714, 2017). "While ALDH1A1 and MYC genes were reported in metastasis of several tumor types and associated with poor prognosis, for CCNG2, a cell cycle checkpoint cyclin upregulated in response to DNA damage, the association to stemness was not clear." (PMID 28938627, 2017). "Statistical analyses between these two groups showed a significant inverse association between MYC transcript levels and disease stage (P=0.030), as well as the tumor size (P=0.011)." (PMID 28480695, 2017). "The notion that inactivation of MYC can cause tumor regression in animal models by eliciting oncogene addiction, makes it an attractive target for therapeutic anti-cancer strategies." (PMID 28505071, 2017). "Highlighting the importance of this mechanism, re-expression of INI1 negatively affected proliferation of MYC-positive INI1-deficient rhabdoid tumor cells." (PMID 28505071, 2017). "Significant over-expression of a similar set of genes in human cancers seems to be correlated with tumor invasiveness, suggesting the importance of MYC association with the NuA4 complex in cancer." (PMID 29321817, 2017). "These chromothripsis-related structural aberrations were associated with amplification of MYCN, and in one tumor, resulted in MYC amplification and overexpression." (PMID 28587062, 2017). "MYC inactivation in T-ALL causes tumor regression, which depends on reactivation of tumor suppressor genes that in turn trigger cellular senescence." (PMID 29100357, 2017). "EPOR knockdown abrogated human tumor cell growth, induced apoptosis through Bim, reduced invasiveness, and caused downregulation of MYC expression." (PMID 28418910, 2017).
tumor (continued). "A loss of either of these tumor suppressors accelerates tumorigenesis in MYC-driven mouse models (for more details see the next section)." (PMID 28333115, 2017). "MYC withdrawal caused complete tumor regression, proposing a strong MYC oncogene addiction in this tumor model." (PMID 28333115, 2017). "We previously reported that T-ALL in this model elicits oncogene addiction, and that MYC inactivation causes tumor regression by triggering cellular senescence." (PMID 29100357, 2017). "JQ1 suppressed proliferation through G1 cell cycle arrest and caused tumor regression and cellular senescence, presenting BETi as a successful strategy to target MYC." (PMID 28505071, 2017). "In the absence of a functional apoptotic response, the strong proliferative signal caused by MYC deregulation can further trigger tumor formation." (PMID 28333115, 2017). "Our results show that the MYC super-enhancer region that carries multi-cancer susceptibility in humans contributes to the formation of multiple tumor types also in mice." (PMID 28583252, 2017). "Biases in genomic data due to tumor purity and other possible factors can give strong association signals; when we removed some of these biases many signals (such as MYC amplification) were diminished or disappeared." (PMID 28749946, 2017). "MYC amplification has been shown to be considerably associated with aggressive tumor phenotypes and poor patients’ survival." (PMID 28480695, 2017). "For instance, amplifications in 8q21 have been associated with high tumour grade, high levels of Ki67 and other proliferation markers, including MYC, MDM2 and CCND1." (PMID 28351365, 2017). "The aggressive primary tumour displayed high-risk features, including overexpression of MYC and >90% cell proliferation, and exhibited rapid clinical progression with <220 days between clinical presentation and death of disease." (PMID 28417956, 2017). "Moving forward, HDMs are highly promising for therapeutic targets for MYC-associated cancers but more specific drugs are needed to be developed to overcome the off-target effects and make these drugs tumor-cell-specific." (PMID 28505071, 2017). "Mechanistically, MYC binding is enriched at neuroendocrine genes in mouse tumor cells and loss of MYC reduces ductal-neuroendocrine lineage heterogeneity, while deregulated MYC expression in KRAS mutant mice increases this phenotype." (PMID 29170413, 2017). "While inhibiting MYC-associated HAT activity aims at antagonizing MYC-driven transactivation of tumor-promoting genes, the goal of targeting HDAC activity is to release the MYC-driven transrepression of tumor suppressor genes." (PMID 28505071, 2017). "None of the patients with pRCC type 1 tumors and the favorable MYC staining patterns died of tumor-related causes during the complete observation period of 141 months." (PMID 29180625, 2017). "So how does the transcriptional signature associated with increased MYC arise in both normal and tumour cells?" (PMID 28398229, 2017). "To evaluate the role of Jdp2 in tumor maintenance we used an shRNA construct to knockdown the levels of Jdp2 in a Dnmt3a-deficient MYC-induced PTCL cell line." (PMID 27690235, 2016). "All these facts suggest that c-MYC-related activation of the WNT/TGF beta pathways is a key component of the ploidy-associated network with the tumour-like properties including stemness and EMT." (PMID 27655693, 2016). "As described by our group in a smaller cohort, MYC increased expression was associated with intestinal-type, deeper tumor extension and the presence of metastasis." (PMID 27863420, 2016).
tumor (continued). "We identify two candidate tumor suppressors whose loss cooperate with MYC over-expression to accelerate lymphomagenesis." (PMID 27982060, 2016). "For example, a gene that encodes a transcription factor protein called MYC is upregulated in most types of tumor, where it supports several aspects of tumor development." (PMID 27460973, 2016). "Although BET inhibitors have a dramatic effect on suppression of tumor growth, there is a possibility that they cause critical damage to normal cell proliferation that is controlled by the MYC-dependent transcriptional pathway and the Wnt signaling pathway." (PMID 27827996, 2016). "As well as providing a potential route to targeting MYC driven tumours, CDK1 inhibition has also been proposed as a route to causing chemosensitivity, enhancing the effects of PARP inhibitors as well as PI3-kinase inhibitors." (PMID 26881434, 2016). "Rather, transcript isoform changes appear linked to tumor-type specific processes, with several of them related to MYC activity, in concordance with recent findings." (PMID 27535130, 2016). "CMS2 (canonical, 37 %) CRC predominantly displayed epithelial signatures with prominent WNT and MYC signalling activation, and more often displayed loss of tumour suppressor genes and copy number gains of oncogenes than the other subtypes." (PMID 27325016, 2016). "A broad body of evidence establishes that deregulated MYC expression causally contributes to multiple aspects of tumor development and that tumors depend on enhanced expression of MYC for growth and survival." (PMID 27460974, 2016). "Over the past years, the typical translocation, involving the MYC oncogene and its variants, has been considered the molecular hallmark of this tumor." (PMID 26453442, 2015). "MAZ was initially described as a protein binding to a 16 bp region of the MYC promoter and has been implicated in transcriptional activation of target genes and regulation of tumor cell proliferation and apoptosis." (PMID 25749382, 2015). "The patients with a MYC abnormality had a significantly higher tumor burden, a higher percentage of medium/high risk MIPI group and genomic instability compared to those without this abnormality." (PMID 26517511, 2015). "Copy number alterations target multiple tumour suppressive/oncogenic loci; however, amplification of MYC is uniquely associated with poor outcome and adenosquamous subtype." (PMID 25855536, 2015). "Deregulation of MYC expression and/or activity is tightly linked to tumour development, as ∼70% of human cancers show aberrant MYC function." (PMID 26555894, 2015). "MYC is a proto-oncogene, which can lead to deregulation of many genes, cause cellular proliferation, and result in tumor formation." (PMID 26170901, 2015). "There was a higher median WBC, higher percentage of patients belonging to the medium-high MIPI risk group and high tumor burden with higher β2-MG for the MYC abnormality group." (PMID 26517511, 2015). "As for SRC and LYN, MYC immunoreactivity or elevated mRNA expression was previously associated with late onset, advanced stage, deeper tumor extension and the presence of metastasis." (PMID 26460485, 2015). "In the study, we observed that tumour ROIs in radical prostatectomy specimens bore chromosomal abnormalities, including MYC amplification/gain, LPL and PTEN loss, TMPRSS2 rearrangement, as well as general aneuploidy." (PMID 24568597, 2014).